ENSG00000207100
Synonyms: LOC124900495
Gene: Small nucleolar RNA gene on chromosome X (133,152,754 to 133,152,892, forward strand). Ensembl gene ENSG00000207100.
Gene Ontology:
Biological process: RNA processing
Cellular component: nucleolus
Homologues: Orthologues: mouse Gm25791 (86% identical), mouse Gm26236 (85% identical). Paralogues in human: SNORA8 (94% identical).